SMCP (sperm mitochondria associated cysteine rich protein)
Description:
Involved in sperm motility. Its absence is associated with genetic background dependent male infertility. Infertility may be due to reduced sperm motility in the female reproductive tract and inability to penetrate the oocyte zona pellucida (By similarity).
Synonyms: MCS; MCSP; HSMCSGEN1
Tractability: Antibody: UniProt places it where antibodies can reach, with high confidence.
Gene: Protein-coding gene on chromosome 1 (152,878,322 to 152,885,047, forward strand). Ensembl gene ENSG00000163206.
Subcellular location: Cytoplasm; Mitochondrion membrane
Gene Ontology:
Molecular function: protein binding
Biological process: flagellated sperm motility; penetration of zona pellucida
Cellular component: mitochondrion; cytoplasm; mitochondrial membrane
Genetic constraint (gnomAD): Loss-of-function variants: 0 observed, 0.0749 expected, observed/expected ratio (o/e) 0, 90% interval 0 to 1.89. That is too few expected variants to judge how well the gene tolerates losing a copy. Missense variants: 137 observed, 144.68 expected, observed/expected ratio (o/e) 0.95, 90% interval 0.82 to 1.09. Synonymous variants: 41 observed, 49.69 expected, observed/expected ratio (o/e) 0.83, 90% interval 0.64 to 1.07.
Homologues: Orthologues: chimpanzee SMCP (96% identical), macaque SMCP (86% identical), pig SMCP (48% identical).
Diseases named in the same sentence as SMCP in open-access papers:
SMCP is named in the same sentence as 15 diseases in open-access papers, as found by Europe PMC text mining. Sharing a sentence is not in itself a finding about the gene and the disease. The quoted sentences say what the papers report.
large cell carcinoma (1 paper, 2013). A malignant epithelial neoplasm composed of large, atypical cells. "SMCP mRNA was preferentially expressed in primary lung cancerous tissues in 5 cases (2 adenocarcinomas, 2 squamous cell carcinomas and 1 large cell carcinoma) than those in adjacent normal counterpart lung tissues." (PMID 24244262, 2013).
lung carcinoma (1 paper, 2013). "SMCP was shown to have a role in tumor initiation by SMCP overexpression and SMCP knockdown using siRNAs in lung cancer cells." (PMID 24244262, 2013). "In this study, we investigated the distributions of SMCP protein, and we found that GFP-fused SMCP protein is expressed in the mitochondria of lung carcinoma cells." (PMID 24244262, 2013).
male infertility (1 paper, 2020). The inability of the male to effect fertilization of an ovum after a specified period of unprotected intercourse. "Knockout of SMCP could lead to decreased sperm motility and male infertility." (PMID 31936222, 2020).
cancer (1 paper, 2013). A tumor composed of atypical neoplastic, often pleomorphic cells that invade other tissues. "RT-PCR analysis was performed to determine the expression of SMCP in human fetal and adult normal tissues and in cancer cells." (PMID 24244262, 2013). "SMCP vt2 was detected in only cancer cells, whereas the wild-type (vt1) form of SMCP was expressed in the testis." (PMID 24244262, 2013). "Since the SMCP protein was reported to be expressed in sperm mitochondria, the cellular localization of SMCP in cancer cells was investigated using a GFP-fused SMCP gene." (PMID 24244262, 2013). "Since SMCP is expressed in the testis and cancer cells, SMCP is a novel cancer-testis (CT) gene." (PMID 24244262, 2013). "We therefore hypothesized that the transcript of SMCP in cancer cells was different from that in the testis." (PMID 24244262, 2013). "Anti-SMCP antibody might therefore be a new useful biomarker for detection of CSCs/CICs that is related to prognosis of cancer patients." (PMID 24244262, 2013). "Indeed, we could detect anti-SMCP antibody in cancer patients' sera by an ELISA assay using SMCP recombinant protein (unpublished data)." (PMID 24244262, 2013). "We detected SMCP mRNA in the testis tissue, but we did not detect SMCP mRNA in any of the cancer cells by qPCR." (PMID 24244262, 2013). "Although SMCP has not been reported by screening using cancer patients' sera, SMCP was reported to be recognized by sera from rats immunized by sperm." (PMID 24244262, 2013). "Since SMCP is expressed in cancer tissues but not in normal tissues except for the testis, SMCP might be a novel CSC/CIC marker and a promising and potential target of CSC/CIC-targeting therapy." (PMID 24244262, 2013).
tumor (1 paper, 2013). "Taken together, the initiation results indicate that an ectopically expressed variant form of SMCP has a role in tumor initiation of CSCs/CICs and that the variant form of SMCP might be a novel CSC/CIC marker and a potential and promising target of CSC/CIC-targeting therapy." (PMID 24244262, 2013). "Tumor growth was significantly suppressed in mice injected with SMCP siRNA1 and siRNA2-transfected LHK2, Lc817 and A549cells compared to that in mice injected with control siRNA-transfected LHK2 cells." (PMID 24244262, 2013). "Taken together, these results indicate that SMCP has a role in the tumor-initiating ability of CSCs/CICs." (PMID 24244262, 2013). "The results obtained by using SMCP-overexpressing cells suggested that SMCP has a role in tumor initiation, and we therefore performed a gene knockdown study using siRNAs." (PMID 24244262, 2013). "To investigate the tumor-initiating ability of SMCP knockdown cells, we injected SMCP siRNA-transfected LHK2, Lc817 and A549 cells into NOD/SCID mice." (PMID 24244262, 2013).
SMCP also shares sentences with these, for which no sentence is quoted: adenocarcinoma (1 paper); breast carcinoma (1); lung adenocarcinoma (1); lung large cell carcinoma (1); lung small cell carcinoma (1); lung squamous cell carcinoma (1); orofacial clefting (1); pancreas carcinoma (1); renal cell carcinoma (1); squamous cell carcinoma (1).